LINC01341 (long independently transcribed non-coding RNA 1341)
Gene: Long non-coding RNA gene on chromosome 1 (246,775,880 to 246,792,392, forward strand). Ensembl gene ENSG00000227953.
Diseases named in the same sentence as LINC01341 in open-access papers:
LINC01341 is named in the same sentence as 4 diseases in open-access papers, as found by Europe PMC text mining. Sharing a sentence is not in itself a finding about the gene and the disease. The quoted sentences say what the papers report.
prostate carcinoma (1 paper, 2017). A carcinoma that arises from epithelial cells of the prostate gland. "We found that hypermethylation of COL4A6, CYBA, LINC01341, and RHCG was highly prostate cancer-specific, suggesting particularly promising diagnostic potential for these genes." (PMID 28052017, 2017).
thyroid cancer (1 paper, 2018). "The results of CNV analyses showed that many differentially expressed lncRNAs loci are accompanied with copy number amplification or deletion, such as LINC01354 and LINC01341 have frequency gain, LINC00595 and LINC01519 have frequency loss in thyroid cancer." (PMID 29923329, 2018). "Moreover, some of those dysregulated lncRNAs genomic loci contains copy number amplification or deletion, such as LINC01354, LINC01341, LINC00595, and LINC01519, suggesting that genomic alterations might involve in part of these lncRNAs dysregulation in thyroid cancer." (PMID 29923329, 2018).
cancer (1 paper, 2017). A tumor composed of atypical neoplastic, often pleomorphic cells that invade other tissues. "Finally, we observed cancer-specific promoter hypermethylation of the verified but uncharacterized long non-coding RNA LINC01341." (PMID 28052017, 2017).
tumor (1 paper, 2017). "Experimental design: Eight novel candidate markers, COL4A6, CYBA, TCAF1 (FAM115A), HLF, LINC01341 (LOC149134), LRRC4, PROM1, and RHCG, were selected from Illumina Infinium HumanMethylation450 BeadChip analysis of 21 tumor (T) and 21 non-malignant (NM) prostate specimens." (PMID 28052017, 2017).